HGF (hepatocyte growth factor)
Diseases named in the same sentence as HGF in open-access papers (continued):
Sharing a sentence is not in itself a finding about the gene and the disease.
End Stage Liver Disease (2 papers, 2018 to 2023). Final stage of a liver disease when the liver failure is irreversible and LIVER TRANSPLANTATION is needed. "The peak GPNMB level correlated with prothrombin activity, prothrombin time-international normalized ratio, Model for End-stage Liver Disease score, and serum hepatocyte growth factor level." (PMID 37941897, 2023).
endometrial tumor (2 papers, 2016 to 2025). "Higher levels of NRP-1 expression in the endometrial tumors were associated with increasing levels of circulating HGF and G-CSF in matching patient serum (p = 0.0166 and 0.0148 respectively)." (PMID 26701889, 2016). "Furthermore, hepatocyte growth factor (HGF) produced by CAFs binds to its receptor on endometrial tumor cells, thereby increasing invasion capacity." (PMID 41228294, 2025).
germ cell tumor (2 papers, 2023). A benign or malignant, gonadal or extragonadal neoplasm that originates from germ cells. "In several cancer models, HGF has been shown to increase both expression of jagged and tumor invasiveness, including human germ cell tumors In addition, HGF has been shown to play a role in collective migration of epithelial cells." (PMID 37903140, 2023). "In previous manuscripts we reported c-MET/HGF expression and the role in testicular germ cell tumors (TGCTs) derived cell lines." (PMID 37509533, 2023).
gingivitis (2 papers, 2021). A disorder involving inflammation of the gums; may affect surrounding and supporting structures of the teeth. "In conclusion, the data obtained in this work demonstrated that EPS from S. mutans does not cause changes in ATP levels in HGF-1 and does not affect their viability, therefore it cannot constitute per se a pathogenic factor in initiating gingivitis associated with dental plaque." (PMID 34104099, 2021).
Glucose intolerance (2 papers, 2022 to 2024). Glucose intolerance (GI) can be defined as dysglycemia that comprises both prediabetes and diabetes. "HGF/VEGF plasmid injection aggravated glucose intolerance in HFD conditions." (PMID 36497083, 2022).
gout (2 papers, 2020 to 2023). A condition characterized by painful swelling of the joints, which is caused by deposition of urate crystals. "Another pro-angiogenic factor, HGF, was also enriched in the sera of flaring patients with gout." (PMID 37810213, 2023).
graft versus host disease (2 papers, 2014 to 2022). An immune system disorder that occurs after allogeneic hematopoietic stem cell transplant and is a reaction of donor immune cells against host tissues. "In addition, graft-versus-host disease (GVHD) could be inhibited by HGF." (PMID 35889092, 2022).
Hematuria (2 papers, 2020 to 2024). The presence of blood in the urine. "They reported that HGF concentration was significantly higher in patients with high symptom scores and positively associated with hematuria and a diagnosis of RC." (PMID 39665773, 2024). "HGF protein concentration was significantly higher in patients with high symptom scores and showed a positive association with hematuria and RC diagnosis." (PMID 33119677, 2020).
Hydrocephalus (2 papers, 2016 to 2022). Hydrocephalus is an active distension of the ventricular system of the brain resulting from inadequate passage of CSF from its point of production within the cerebral ventricles to its point of absorption into the systemic circulation. "For example, it was found that intraventricular administration of hepatocyte growth factor (HGF) treats hydrocephalus due to TGF-β overexpression, and this represents a more favorable pharmacological target." (PMID 36050779, 2022). "Intracerebroventricular infusion of recombinant human hepatocyte growth factor, which antagonizes the fibrosis-inducing effect of TGF-β1, for 7 or 14 days, improved the memory, ventricle size, CSF flow, and meningeal fibrosis in mice with TGF-β1 injection-induced hydrocephalus." (PMID 26846184, 2016).
Inguinal hernia (2 papers, 2024). Protrusion of the contents of the abdominal cavity through the inguinal canal. "The presence of HGF receptors in the processus vaginalis may indicate the role of HGF in triggering epithelial-mesenchymal transformation during inguinal hernia closure." (PMID 38816716, 2024).
insulinoma (2 papers, 2015 to 2016). "A lower RNA expression of the inhibitor of matriptase SPINT1 was detected in the insulinoma metastases, potentially contributing to increased activity of matriptase to participate in HGF activation." (PMID 26435753, 2015). "This study demonstrated the differential expression of four genes belonging to the HGF/MET system between G1 insulinomas and liver metastases of insulinomas, suggesting the participation of this pathway in the later stages of tumorigenesis." (PMID 26435753, 2015). "A higher expression of MET (P = 0.0115), HGF (P = 0.0183) and ST14 (P = 0.0453) mRNA was observed in the three metastases in comparison to G1 insulinomas." (PMID 26435753, 2015). "The relevance of HGF in lipid-induced toxicity has been confirmed even in nonhepatic cells such as the insulinoma-derived cell line RINm5F, where the growth factor repressed the free fatty acid-induced apoptosis by counteracting oxidative stress." (PMID 27143995, 2016). "The final effect of the increased expression of HGF, its activator (matriptase) and its specific receptor (MET) together with a decreased expression of one potent inhibitor of matriptase (SPINT1) is probably a contribution to tumoral progression and metastatization in insulinomas." (PMID 26435753, 2015). "The HGF/MET system has not been systematically investigated in insulinomas." (PMID 26435753, 2015). "An interesting finding of the present study was the absence of RNA expression of HGFAC, considered the most powerful activator of pro-HGF in HGF, indicating that in insulinomas, matriptase (and maybe other proteins not evaluated in this study, such as hepsin) is responsible for pro-HGF proteolysis." (PMID 26435753, 2015).
invasive carcinoma (2 papers, 2015 to 2016). A carcinoma that is not confined to the epithelium, and has spread to the surrounding stroma. "The fact that no changes were detected in latency in the prevention arm of our study suggests that early changes in the HGF/cMET axis (i.e., prior to invasive carcinoma) may not be as easily targeted, or are not causative in BBC tumorigenesis." (PMID 27057482, 2016).
invasive ductal adenocarcinomas (2 papers, 2015). "However, when proceeding to PanIN or even invasive ductal adenocarcinomas, expression of both cMET and HGF greatly increases." (PMID 25884642, 2015).
Jaundice (2 papers, 2014 to 2016). Yellow pigmentation of the skin due to bilirubin, which in turn is the result of increased bilirubin concentration in the bloodstream. "As a result of this study, HGF was effective in the irreversible jaundiced groups and ineffective in the reversible jaundice groups." (PMID 27540507, 2016).
keratitis (2 papers, 2017 to 2022). A corneal disease that is characterized by inflammation of the cornea. "The present study highlights the anti-inflammatory and restorative function of HGF in keratitis, expanding the potential therapeutic application of HGF to infectious inflammatory ocular surface disorders." (PMID 35017561, 2022). "Diffusely distributed HGF staining throughout the corneal stroma in corneas with keratitis compared to naïve controls demonstrated that exogenously administered HGF penetrates damaged stroma with high efficacy." (PMID 35017561, 2022). "Taken together our data suggest that the barrier function of the corneal epithelium is disrupted in LPS-induced keratitis, which allows the stromal penetration of topically applied HGF." (PMID 35017561, 2022). "Our data demonstrate that topical HGF treatment significantly reduces the severity of inflammatory opacity to preserve corneal transparency following keratitis." (PMID 35017561, 2022). "Using this model, we investigated the therapeutic potential of HGF in suppressing the development of corneal opacity to preserve transparency in LPS keratitis." (PMID 35017561, 2022). "Following keratitis induction, corneas were topically treated with 0.1% HGF or PBS thrice daily for 5 days." (PMID 35017561, 2022). "HGF-treated corneas showed normalized corneal structure and reduced expression of pro-inflammatory cytokine, demonstrating that HGF restores corneal architecture and immune quiescence in corneas with LPS-induced keratitis." (PMID 35017561, 2022). "Taken together, these results indicate that HGF treatment suppresses corneal infiltration of inflammatory cells and their expression of pro-inflammatory cytokine IL-1β during LPS keratitis." (PMID 35017561, 2022). "In conclusion, we have shown that the novel peptide H-RN, which we derived from HGF, effectively attenuated keratitis in vivo and in vitro through blocking the NF-κB and MAPK signaling pathways." (PMID 28125988, 2017). "In the present study, we observed increased expression of α-SMA following LPS injection which was significantly reduced following HGF treatment compared to PBS treatment, suggesting topical application of HGF suppresses myofibroblast formation in LPS-induced keratitis." (PMID 35017561, 2022). "Here, we investigated whether HGF has the capacity to suppress infectious inflammatory corneal opacity using a new model of LPS-induced keratitis." (PMID 35017561, 2022). "Next, we sought to determine whether topically applied HGF penetrates corneal epithelium into the stroma in the new model of LPS-induced keratitis." (PMID 35017561, 2022). "As the transparency of the cornea is required for light transmission is dependent on its uniquely organized cellular and collagen architecture, we investigated the effect of HGF in preserving normal cellular architecture and corneal thickness following LPS keratitis." (PMID 35017561, 2022). "To confirm the efficacy of HGF in reducing corneal opacity formation and preserving transparency following LPS keratitis, we investigated whether HGF inhibits the expression of α-smooth muscle actin (α-SMA), a marker of fibrosis, following LPS injection." (PMID 35017561, 2022). "Similarly, we observe disruption of the corneal epithelium in our new model of LPS-induced keratitis, thus allowing HGF, a protein with a molecular weight of 84 kDa, to penetrate through the epithelium and into the corneal stroma." (PMID 35017561, 2022). "Our data demonstrate that topical HGF administration reduces the development of corneal opacity by suppressing the expression of pro-fibrotic marker α-SMA in the cornea, improving corneal transparency following keratitis compared to PBS control." (PMID 35017561, 2022).
left ventricular hypertrophy (2 papers, 2025). Enlargement of the LEFT VENTRICLE of the heart. "Zhang et al25 reported that HGF levels were higher in patients with AL (n = 43) or ATTR-CM (n = 29) compared to patients with HF with reduced ejection fraction or with left ventricular hypertrophy but without CA." (PMID 40570404, 2025).
leiomyoma (2 papers, 2013 to 2023). A well-circumscribed benign smooth muscle neoplasm characterized by the presence of spindle cells with cigar-shaped nuclei, interlacing fascicles, and a whorled pattern. "Leptin induces a tumor-friendly microenvironment through upregulation of pro-inflammatory (IFNγ, IL-8, IL-6, GM-CSF, MCP-1, and TNF-α), fibrotic (TGF-β1, TGF-β2, and TGF-β3), and angiogenic (VEGF-A, HGF, and Follistatin) factors in human leiomyoma cells." (PMID 36771423, 2023).
male infertility (2 papers, 2024 to 2025). The inability of the male to effect fertilization of an ovum after a specified period of unprotected intercourse. "Our MR analysis between gut microbiota, inflammatory cytokines, and male infertility provides evidence for a causal relationship between gut microbiota and male infertility and the role of hepatocyte growth factor as a mediator." (PMID 38711980, 2024). "In addition, HGF may have mediated 38.9% of the causal effect of Bacteroides on male infertility." (PMID 38711980, 2024). "In this study, we demonstrate that exogenous GDNF enhances hepatocyte growth factor (HGF)-induced in vitro organization of Sertoli cells within a Matrigel-based 3D culture system, providing new insights into testicular organization and potential therapeutic implications for male infertility." (PMID 40402398, 2025).
mesenchymal tumor (2 papers, 2015 to 2020). "We analyzed a total of 484 adult-type malignant mesenchymal tumors by MET fluorescence in situ hybridization and MET and hepatocyte growth factor immunohistochemistry." (PMID 25844809, 2015).
moyamoya angiopathy (2 papers, 2013 to 2024). "Whether it plays a role in the initiation of other cascades remains uncertain however, it is clear that inhibiting HGF expression in the carotids could prove beneficial in the treatment of moyamoya disease." (PMID 23966972, 2013). "Additionally, hypoxia inducible factor-1α, which promotes smooth-muscle cell proliferation in the presence of bFGF and HGF, is present in elevated levels in moyamoya disease." (PMID 23966972, 2013). "In addition to HGF being densely found in the carotid fork, its CSF level is markedly elevated in moyamoya disease, suggesting that HGF may be a key protein for pathogenesis of moyamoya disease." (PMID 23966972, 2013).
mucositis (2 papers, 2000 to 2025). Mucositis is inflammation and damage of the mucous membranes lining the mouth and other parts of the gastrointestinal (GI) tract. "The possible mechanism of treatment of mucositis in the present study by GA may be exerted through the increase of HGF expression, although its direct role in the healing of mucositis is also discussed." (PMID 40129451, 2025).
muscular atrophy (2 papers, 2014 to 2022). The loss of muscle tissue due to inactivity or disease. "In this study, we demonstrate that HGF-mediated activation of the satellite cells in hypoxia-induced muscular atrophy combined with LIF can reverse the loss of muscle mass." (PMID 24963862, 2014).
muscular dystrophies (2 papers, 2014 to 2015). "Our findings identify a critical role for HGF during inflammation resolution and provide new mechanistic insight into how modulation of NF-κB/p65 attenuates muscular dystrophy." (PMID 25906153, 2015).
myelofibrosis (2 papers, 2020 to 2025). A partial or complete replacement of the bone marrow stroma by fibrous tissue. "This mutation correlates with elevated levels of IL-1RA, IL-2R, IL-6, IL-12, IP-10, hepatocyte growth factor, and monokine induced by IFN-γ in primary myelofibrosis patients." (PMID 32341381, 2020).
myeloid malignancies (2 papers, 2014 to 2021). "Hence, it is unlikely that the very frequent activation of the HGF/Met axis observed in myeloid malignancies results from MET mutation." (PMID 25119536, 2014). "These new therapeutic options should be of interest in myeloid malignancies, notably MPNs, a group of diseases withchronic inflammation wherevery high HGF levels are frequent." (PMID 25119536, 2014). "For example, basophils reportedly express and release vascular endothelial growth factor and hepatocyte growth factor, both of which may contribute to the increased angiogenesis and tissue remodeling in myeloid neoplasms." (PMID 34731787, 2021). "The role played by HGF in the maintenance of stem cells and in the survival, proliferation and migration potential of malignant cells, suggested that HGF expression levels could have independent prognostic value in myeloid malignancies." (PMID 25119536, 2014). "The object of this review is to gather and summarise published studies of the MET gene in myeloid malignancies, and to provide evidence that drugs currently used in solid tumours to block the HGF/Met axis should also be considered for the therapy of chronic myeloid malignancies." (PMID 25119536, 2014).
myocarditis (2 papers, 2012 to 2025). Myocarditis is a condition that is characterized by inflammation of the heart muscle (myocardium). "MSCs increased significantly the myocardial expression of HGF and decreased the expression of the proinflammatory cytokines TNFα, IL1β and IL6 as well as the severity of myocarditis and ameliorated the left ventricular dysfunction measured by conductance catheter." (PMID 22815907, 2012).
myxoma (2 papers, 2020 to 2024). A benign soft tissue neoplasm characterized by the presence of spindle and stellate cells, lobulated growth pattern, and myxoid stroma formation. "Furthermore, IPA further revealed that the dysregulated genes in myxoma-derived CSCs are components of several canonical pathways such as HGF and IGF-1 signalling, telomerase signalling, stem cell pluripotency, and stem cell signalling among others." (PMID 32330934, 2020). "The hyperactive signals in many malignant tumours, such as MDK, HGF, chemerin and GDF15 signalling, were found to be sent primarily by myxoma tumour cells." (PMID 38318640, 2024).
oropharyngeal squamous cell carcinoma (2 papers, 2014 to 2024). "It focused on the longitudinal changes in serum levels of specific factors like IL-6, IL-8, VEGF, HGF, and GRO-α in 30 patients undergoing chemoradiation therapy for stage III/IV oropharyngeal squamous cell carcinomas." (PMID 38672104, 2024).
papillary renal cell carcinoma (2 papers, 2018 to 2025). A rare subtype of renal cell carcinoma, arising from the renal tubular epithelium and showing a papillary growth pattern, which typically manifests with hematuria, flank pain, palpable abdominal mass or nonspecific symptoms, such as fatigue, weight loss or fever. "In human cancer, three different means of MET activation have been reported: HGF-dependent (autocrine or paracrine system); overexpression of MET (oligomerization of MET causes reciprocal activation); and activating point mutations (such as hereditary papillary renal cell carcinoma)." (PMID 29890660, 2018).
parasite infection (2 papers, 2019 to 2024). "During sporozoite infection, Kupffer cells secrete hepatocyte growth factor (HGF) which induces apoptosis in hepatocytes of early liver schizonts, thus preventing the progression of further parasitic infection." (PMID 31662766, 2019).
peritonitis (2 papers, 2012 to 2020). Inflammation of the peritoneum (tissue that lines the abdominal wall and covers most of the organs in the abdomen). "This would indicate that HGF may contribute to the denudation of the mesothelium and increase fibrogenesis during peritonitis." (PMID 22577250, 2012). "These researchers also observed an increase in the levels of HGF in dialysis effluent obtained from patients with peritonitis when compared to levels detected in non-infected PD fluid." (PMID 22577250, 2012).
pregnancy hypertension (2 papers, 2023 to 2024). "We found that GROA and IL-9 exhibited causal relationships with pregnancy hypertension, while interleukin-10 (IL-10) and hepatocyte growth factor (HGF) demonstrated causal relationships with PE." (PMID 38362587, 2023).
primary effusion lymphoma (2 papers, 2019 to 2021). A large B-cell lymphoma located in the body cavities, characterized by pleural, peritoneal, and pericardial fluid lymphomatous effusions and that is always associated with human herpes virus-8 (HHV-8). "The HGF/c-MET pathway appears further largely activated in malignant cells from primary effusion lymphoma (PEL): here the expression of plexin B1 is required for c-MET-mediated survival of PEL cells." (PMID 30642077, 2019).
primary lymphedema (2 papers, 2014 to 2024). A congenital condition that results in swelling in the arms or legs, and can occur during adolescence or adulthood. "To contribute to this area of study, in this report, we describe a novel loss-of-function HGF mutation identified in a multigenerational family with primary lymphedema." (PMID 38791500, 2024). "They concluded that HGF and cMET mutations were likely causal for primary lymphedema and/or susceptibility genes for acquired lymphedema, an affliction that impacts an estimated 15% of all cancer survivors." (PMID 25383712, 2014).